CNOT7 (CCR4-NOT transcription complex subunit 7)
Diseases named in the same sentence as CNOT7 in open-access papers (continued):
Sharing a sentence is not in itself a finding about the gene and the disease.
sterility (1 paper, 2022). "Mice with the loss of PARN-regulatory protein (Cnot7-knockout mice), besides compromised deadenylation, suffer from sterility because of oligo-astheno-teratozoospermia and defective maturation of spermatids." (PMID 35565367, 2022).
tumor (8 papers, 2016 to 2025). "In summary, these results revelated that high CNOT7 expression in tumor tissues was linked to resistance to radiotherapy." (PMID 41249119, 2025). "In CRC xenograft model, CNOT7 deficiency significantly inhibited tumor growth and made these tumors more sensitive to radiotherapy-induced DNA damage." (PMID 41249119, 2025). "Additionally, the combination of STL127705, an inhibitor of the XRCC6/XRCC5 heterodimer, with radiotherapy notably suppressed tumor growth in patient-derived xenograft (PDX) and cell line mouse transplant tumor models, especially in the context of CNOT7 deficiency." (PMID 41249119, 2025). "Consistently, representative cases of rectal magnetic resonance imaging (MRI) showed tumor shrinkage after radiotherapy in patients with CNOT7 low expression, whereas tumors in patients with CNOT7 high expression exhibited stable disease." (PMID 41249119, 2025). "In this study, we combined publicly available data and tumor samples from our center and found that CNOT7 protein is widely overexpressed in CRC tissues." (PMID 41249119, 2025). "We discovered that CNOT7 knockdown tumors had slower tumor growth rate, smaller volume and weight and was sensitive to radiation treatment compared to the HCT116 tumors." (PMID 41249119, 2025). "High CNOT7 was found in 50% (45/90) of cases, correlating with higher tumor grade, hormone receptor negativity, and increased lymph node involvement." (PMID 40806280, 2025). "We sought to establish a correlation between the levels of CNOT7 and LAIR-1 in the blood, clinically assessing their association with tumor-node-metastasis TNM staging." (PMID 40806280, 2025). "Comet assay showed that XRCC6 knockdown significantly increased tail length in CNOT7 overexpression cells, a marker of DNA damage, indicating that the tumor cells experienced more severe DNA damage." (PMID 41249119, 2025). "Immunohistochemical revealed a notably decrease in protein levels of XRCC6 and 53BP1 in CNOT7 knockdown transplanted tumor." (PMID 41249119, 2025). "High expression of CNOT7 drives tumor cell autonomous metastatic potential, which requires its deadenylase activity." (PMID 38985240, 2025). "CNOT7 is a key cytoplasmic mRNA deadenylase whose expression is altered in a variety of human cancers, which suggests its carcinogenic role in tumor development." (PMID 40806280, 2025). "Beyond its role in cell growth, CNOT7 has also been shown to influence the tumor immune microenvironment and contribute to NK cell resistance." (PMID 40806280, 2025). "We demonstrate that higher expression of Cnot7 drives tumor cell autonomous metastatic potential, which requires its deadenylase activity." (PMID 26807845, 2016). "Quantitative real time polymerase chain reaction analysis confirmed that Cnot7+/- mice expressed Cnot7 transcript approximately two-fold lower than wildtype mice in the spleen and tumor." (PMID 26807845, 2016). "Lung colonization assays were therefore performed by intravenous injection of Cnot7-depleted tumor cells into the tail vein of mice." (PMID 26807845, 2016). "Wild type tumor cells were then orthotopically implanted into Cnot7+/- and Cnot7+/+ mice and animals were aged for 28 days prior to necropsy." (PMID 26807845, 2016). "In this study we extend these results by demonstrating that transcriptional decay, mediated by the deadenylation activity of Cnot7 is also an important determinant in tumor progression." (PMID 26807845, 2016). "Immunohistochemistry also indicated that CNOT7 was higher in tumor tissues." (PMID 41249119, 2025). "Increasing evidence highlight CNOT7 function in tumor initiation and progression." (PMID 41249119, 2025). "In other tumors, mRNA level of CNOT7 is also higher in tumor tissues." (PMID 41249119, 2025). "Further investigations into the possible roles of CNOT7 in metastatic progression may reveal additional important insights into tumor autonomous metastatic mechanisms." (PMID 40806280, 2025).
tumor (continued). "Previous studies have demonstrated that CNOT7 promotes tumor proliferation and progression." (PMID 41249119, 2025). "Notably, this effect was more pronounced in the CNOT7 knockdown group, showing a stronger tumor-suppressive effect." (PMID 41249119, 2025). "Moreover, we measured the mRNA expression of CNOT7 in OS tissues and found that the CNOT7 expression in OS tumor tissues was remarkedly increased." (PMID 35156522, 2022). "Therefore, we hypothesized that CNOT7 depletion might reverse NK cell resistance by influencing the tumor immune microenvironment of HCC." (PMID 32160402, 2020). "CNOT7 and STAT1 expression levels were determined in tumor and healthy tissues of patients with HCCBC." (PMID 32160402, 2020). "CNOT7 expression was significantly higher in tumors than in cirrhotic hepatic tissues, whereas STAT1 was obviously down‐regulated in tumor tissues (both P < 0.01)." (PMID 32160402, 2020). "To investigate whether CNOT7 knockdown enhances the CRC radiosensitivity in vivo, we constructed a mouse transplant tumor model." (PMID 41249119, 2025). "An immunosuppressive TME, potentially fostered by elevated CNOT7 activity, might lead to an upregulation or enhanced function of LAIR-1, thereby promoting NK cell anergy or exhaustion and contributing to tumor progression and immune evasion." (PMID 40806280, 2025). "For several genes, most notably CNOT7, GDI1 and SLC25A37, there are a subset of tumours that showed homozygous deletion and thus inhibition/suppression of CNOT8, GDI2 or SLC25A28, respectively, would be predicted to provoke cellular lethality/reduced cancer cell fitness." (PMID 40968372, 2025). "Immunohistochemistry for CNOT7 and STAT1 protein expression in 49 paired HCCBC and cirrhotic hepatic tissues revealed that these proteins were expressed predominantly in the cytoplasm in tumor and cirrhotic hepatic tissues." (PMID 32160402, 2020). "CNOT7 expression was increased, whereas STAT1 expression was decreased in HCC tumor tissues." (PMID 32160402, 2020). "CNOT7 and STAT1 expression levels in tumor and normal liver tissues." (PMID 32160402, 2020). "Cnot7 knockdown consistently reduced pulmonary metastasis without significant effect on primary tumor mass in vivo." (PMID 26807845, 2016). "No consistent difference in tumor mass or metastasis was observed suggesting the primary role of Cnot7 in metastatic progression is tumor cell-autonomous." (PMID 26807845, 2016). "Consistent with previous observations, overexpression of CNOT7 promoted tumor cell metastatic potential but expression of CNOT7 E247A/Y260A or CNOT7 M141R showed no change in metastasis compared to control." (PMID 26807845, 2016). "To test if reduction of Cnot7 expression in the stroma influenced metastasis, we then crossed C57BL/6J Cnot7+/- to FVB/NJ or Balb/cJ mice to generate Cnot7+/- and Cnot7+/+ mice that are immune-tolerant to the FVB- or BALB-derived tumor cells, respectively." (PMID 26807845, 2016). "Collectively, our data support a model of CNOT7, TOB1, CNOT1, and RNA-binding proteins collectively exerting post-transcriptional control on a metastasis suppressive transcriptional program to drive tumor cell metastasis." (PMID 26807845, 2016). "Additionally, we examined the tissue expression of CNOT7 in BC samples categorized as metastatic or non-metastatic tumors, as well as in adjacent non-tumor tissue margins." (PMID 40806280, 2025). "In this experiment, our results indicated that CNOT7 knockdown altered TGF‐β1 production of HCC and IFN‐γ production of NK cells, suggesting that CNOT7 knockdown might reverse NK cell resistance by improving the tumor immune microenvironment of HCC." (PMID 32160402, 2020). "We therefore selected Cnot8 and its highly conserved paralog Cnot7 to determine whether the deadenylation function of CCR4-NOT plays a critical role in tumor progression." (PMID 26807845, 2016).
tumor (continued). "CNOT7 is an important subunit of the eukaryote CCR4-NOT protein complex, and it may participate in the regulation of the transcription of multiple tumor microenvironment related proteins." (PMID 35156522, 2022).
cancer (7 papers, 2014 to 2025). A tumor composed of atypical neoplastic, often pleomorphic cells that invade other tissues. "It was suspected that HDAC2 regulates CNOT7 expression by regulating downstream cancer-related signaling pathways." (PMID 38985240, 2025). "High expression of CNOT7 has been reported to be a significant factor in the development of various cancers." (PMID 40806280, 2025). "This was evidenced by elevated CNOT7 expression levels correlating with the increased secretion of TGF-β1 by HCC cancer tissue, subsequently leading to reduced IFN-γ secretion by NK cells." (PMID 40806280, 2025). "The results showed that the expression of TAOK1, CMTM6 and CNOT7 were significantly lower in the adjacent cancers, while the expression of WASF3 was significantly higher in the adjacent cancers." (PMID 34336682, 2021). "Previous studies have reported CNOT7 expression was increased in various cancers." (PMID 38985240, 2025). "It remains to be investigated how CNOT7 and CNOT8 contribute to the development and progression of cancer." (PMID 25191340, 2014). "There are some reports that CNOT7 and CNOT8 are relevant to the development and progression of cancer." (PMID 25191340, 2014). "Future research should target other CCR4-NOT complex subunits in other cancer types and examine the non-coding RNA (ncRNA) signature for CNOT7 induction and its relation to multidrug resistance in metastatic BC treatment." (PMID 40806280, 2025). "For instance, while MITF, SPDEF, CNOT7, BTK, PAF1, and PAX5 seem to be novel key regulators in the context of HPV-induced carcinogenesis, they are apparently already known to play essential roles in other cancer entities." (PMID 30918060, 2019). "We identified potential novel upstream regulators (e.g., CNOT7, SPDEF, MITF, and PAX5) controlling distinct clusters of genes within the HPV-host cell network as well as distinct factors (e.g., CPPED1, LCP1, and TAGLN) with essential functions in cancer." (PMID 30918060, 2019).
infection (4 papers, 2018 to 2025). The state of being infected such as from the introduction of a foreign agent such as serum, vaccine, antigenic substance or organism. "We observed that BPXV infection results in a progressive decrease in CNOT7 expression from its basal level, the lowest being at 9 to 18 hpi (Fig. 3ci–ii)." (PMID 36280692, 2022). "However, the levels of both CNOT3 and CNOT7 were markedly reduced after infection with both serotypes." (PMID 29593045, 2018). "Following infection of HeLa cells with either Ad5 or Ad12, levels of CNOT1, CNOT3, CNOT4, and CNOT7 were monitored by Western blotting." (PMID 29593045, 2018). "Given that L. pneumophila often targets host processes with multiple effectors (e.g., at least nine effectors influence protein translation during infection), we next determined whether multiple effectors might target CNOT7/8, or other subunits of CCR4−NOT." (PMID 39699231, 2025).
heart disease (1 paper, 2020). "The combined use of GWAS studies and cardiac model systems in this study has enabled us to connect CNOT1, CNOT7 and, overall, CCR4-NOT complex function to cellular and whole-heart phenotypes in the context of human heart disease." (PMID 32471864, 2020).
CNOT7 also shares sentences with these, for which no sentence is quoted: dilated cardiomyopathy (1 paper); gastric cancer (1); Glioblastoma multiforme (1); leukemia (1); lung carcinoma (1); male infertility (1); Pleural effusion (1); rectum cancer (1); steatosis (1); teratozoospermia (1).